SNORD45A (small nucleolar RNA, C/D box 45A)
Synonyms: U45a; RNU45A
Gene: Small nucleolar RNA gene on chromosome 1 (75,787,889 to 75,787,972, forward strand). Ensembl gene ENSG00000207241.
Gene Ontology:
Biological process: RNA processing
Cellular component: nucleolus
Homologues: Orthologues: chimpanzee SNORD45A (100% identical), macaque SNORD45A (99% identical), rabbit SNORD45A (95% identical), guinea pig SNORD45A (94% identical), mouse Gm24494 (92% identical), pig SNORD45A (89% identical), rat Snord45a (89% identical). Paralogues in human: SNORD45C (82% identical), SNORD45B (74% identical).